FGFR1 (fibroblast growth factor receptor 1)
Diseases named in the same sentence as FGFR1 in open-access papers (continued):
Sharing a sentence is not in itself a finding about the gene and the disease.
cancer (continued). "Although small, these differences affected important signaling pathways (NGF-stimulated transcription, IL-10 signaling, PERK activity) and cancer genes (CBFA2T3, ETV4, FGFR1, GLI1, SGK1, and STAT3)." (PMID 38968069, 2024). "This collateral signaling pathway then paradoxically leads to increased cancer cell growth in FGFR1 amplified cells treated with FGFR1 inhibitors and highlights a challenge of FGFR inhibitor use in cancer treatment." (PMID 38553760, 2024). "The role of FGF/FGFR signaling in promoting glycolysis has been reported in other cancers, whereas our finding emphasize that CAF-derived FGFs can promote glycolysis in SCLC cells via FGFR1 signaling." (PMID 39722014, 2024). "Previous studies have reported the interaction between PTK7 and ROR2, FGFR1, or EGFR in cancer cells." (PMID 37569547, 2023). "Fgf9 from tuft cells is predicted to target Fgfr1 on fibroblasts in both PRN and PRT, and epithelial cells through Fgfr1 or Fgfr2 in PRT cancer model." (PMID 37386128, 2023). "This inhibitor differs from earlier TKIs with FGFR‒targeted activity due to its high selectivity for FGFR1, FGFR2, and FGFR3, making this inhibitor particularly attractive for the treatment of FGFR-driven cancers." (PMID 37715207, 2023). "Among these potential druggable alterations, EGFR, KRAS, and PIK3CA gene alterations were the most common, while CDK pathway (CDK4/6, CDKN2A/2B), FGFR1/2/3, BRAF, RET was uncommon across pan-cancer." (PMID 36910668, 2023). "A recent pan-cancer next-generation sequencing profiling demonstrated that ~7% of cancers harbor gain-of-function FGFR aberrations, with varying frequencies between family members (FGFR1 > FGFR3 > FGFR2 > FGFR4)." (PMID 36839989, 2023). "Disrupter drugs such as PD173074 and bemarituzumab are the potent and selective blockers of FGFR1 and FGFR3, and FGFR2b, respectively, and are used to treat different cancers." (PMID 37108717, 2023). "Both the overactivated FGFR1 signaling and the overexpressed FOXQ1 are oncogenic factors that promote the proliferation, invasiveness, and progression of cancer cells 3-5, 21-26." (PMID 36778115, 2023). "The cyclic peptide F8 effectively prevented FGF1–FGFR1 interactions and reduced FGF1-induced proliferation of FGFR1-expressing cancer cells." (PMID 37243023, 2023). "Some studies also found that miR‐15a‐5p is weakly expressed in various human cancers, and inhibits proliferation and metastasis of PAAD by directly targeting FGFR1 and promotes apoptosis." (PMID 36457244, 2023). "Since not all RTKs were covered by RPPA study, we examined Cancer Dependency Map Project, which systematically analyzed genetic vulnerabilities of cancer cells including MPM cell lines (n = 18), and identified FGFR1 as an essential gene for MPM." (PMID 36765038, 2023). "FGFR1 amplification and gene fusions have also been described in RMS with an active role cancer cell proliferation." (PMID 36839989, 2023). "The distribution of FGFR3 fusion differed from that of FGFR1 and FGFR2 fusions, indicating that the distribution of FGFR fusion genes is cancer type‐dependent." (PMID 37537783, 2023). "In this report, we confirmed that the effect of upstream kinases in facilitating LDHA Y10 phosphorylation is specific to FGFR1, indicating that the tyrosine kinase responsible for LDHA Y10 phosphorylation is cancer cell-type specific." (PMID 35525866, 2022). "We investigated clinically relevant RTK fusion genes, namely ABL1, ALK, ERBB2, FGFR1-4, NTRK1-3, RET, and ROS1, because they are among the most frequent druggable cancer molecular biomarkers." (PMID 36009413, 2022). "In KRAS-mutant cancers, trametinib (MEK inhibitor) provokes a compensatory response involving the fibroblast growth factor receptor 1 (FGFR1), resulting in signaling rebound and adaptive drug resistance." (PMID 35251972, 2022). "In cancer stem cells, ADAMDEC1 solubilizes FGF2 to induce FGFR1, upregulating ADAMDEC1 expression to maintain its stemness." (PMID 35379209, 2022).
cancer (continued). "Pan-cancer drug target RTK fusions also include the moieties of ALK, ERBB2, FGFR1-4, MET, RET, and ROS1 genes." (PMID 36009413, 2022). "Re-introduction of miR-3116 resulted in the decrease in FGFR1 level, inhibited the PI3K/AKT pathway, and re-sensitized cancer cells to treatment." (PMID 34830951, 2021). "Both Dovitinib and BGJ398 have been used in clinical trials for several cancers with defined FGFR genetic alterations, while PD166866 is a highly selective inhibitor towards FGFR1 and other kinases such as c-Src, PDGFR, and EGFR." (PMID 33456711, 2021). "For example nestin, a class VI intermediate filament protein found in the cell cytoplasm, and a CSC marker; and fibroblast growth factor receptor 1 (FGFR1), a tyrosine kinase receptor which enhances cancer cell proliferation and migration." (PMID 33637089, 2021). "Affected genes included FGFR1, IRS1, CLDN4, GRB7, and VCAN, while EZR and MYC were commonly affected in at least four out of five progression stages of the selected cancer levels." (PMID 34069906, 2021). "Recently, studies in EGFR-positive cancer cells have shown that sustained activation of STAT3, due to enhancement of its binding to FGFR1, plays a key role in the acquisition of resistance to EGFR inhibitors." (PMID 34830951, 2021). "Copy number amplification events in CCND1, CCND3, CDK6, ERBB2, FGFR1, MET, and PIK3CA also showed higher expression compared to wild types across various cancer types." (PMID 34429404, 2021). "Multiple phase I/II/III trials on the FGFR1-4 irreversible inhibitor futibatinib are running in patients with advanced cancers harboring FGFR aberrations, with encouraging preliminary results in FGFR-1 mutant primary brain tumors." (PMID 34209513, 2021). "The expression of FGFR1 isoforms on PDAC cells can be modulated by the stroma, with PSCs inducing cancer cells to switch to the mesenchymal FGFR1 IIIc isoform." (PMID 33918004, 2021). "Mechanistically, α6 positively regulates the expression of fibroblast growth factor receptor 1 (FGFR1) through a ZEB1/YAP transcription complex, leading to increased expression of multiple SC factors in cancer cells." (PMID 34715893, 2021). "CNAs of kinases, including ERBB2, FGFR1, and EGFR, were correlated with overexpressed proteins in substantial fractions of the same cancer types." (PMID 34552204, 2021). "Huang and co-workers showed that in addition to the proliferative effect on hepatoma cells, FGFR1 ectopic expression also upregulates VEGF expression, which in turn enhances angiogenesis necessary for later stages of cancer progression." (PMID 34830951, 2021). "Regarding structural variations, BRCA-derived PDX models had clear, frequent amplifications and deletions in FGFR1 and PTEN, respectively, as compared to other cancer types." (PMID 34429404, 2021). "FGFR2 was the highest overexpressed kinase in both mRNA (mRNA overexpression rate, RNA = 21%) and protein (PRO = 23%) levels within a cancer cohort (UCEC), followed by FGFR1 (RNA = 18%, PRO = 23%, in LUAD)." (PMID 34552204, 2021). "Treatment of RTK-driven cancer cell lines with zotatifin for 24 h resulted in dose dependent downregulation of HER2, FGFR1 and FGFR2 protein levels, as well as cyclin D1 (a zotatifin target gene)." (PMID 34900714, 2021). "Overexpression of fibroblast growth factor receptor 1 (FGFR1) has been demonstrated in numerous tumors and thereby constitutes a convenient molecular target for selective cancer treatment." (PMID 33962559, 2021). "First, we grouped the 9736 TCGA cancer cohorts into high or low RNA expressions of EGFR, mTOR, NOS2, TGFB1, mTOR, and FGFR1 and compared the survival of cohorts from the two groups." (PMID 33842373, 2021). "Fibroblast growth factor receptor 1 (FGFR1) has recently been identified as a promising novel therapeutic target and prognostic marker in different types of cancer." (PMID 33989301, 2021).
cancer (continued). "Knockdown or inhibition of either FGFR1 or FGFR2 limits the ability of pancreatic cancer cells to form spheroids, a characteristic of cancer stem cells, suggesting an involvement of FGF signalling in maintaining stemness." (PMID 33918004, 2021). "FGF2 has been heavily implicated as a proangiogenic factor, promoting endothelial proliferation and migration following FGFR1/2 signalling and VEGF/angiopoietin 2 secretion, and has been shown to mediate resistance to VEGFR targeted therapy in cancer." (PMID 34830836, 2021). "FGFR1 is a member of the fibroblast growth factor receptor (FGFR) family, and is known to be involved in the progression of different cancer types, including bladder cancer." (PMID 32695477, 2020). "The latest study from a phaseIclinical trial suggested that rogaratinib, a novel kinase inhibitor of FGFR1-4, resulted in an encouraging antitumor activity, if screened by FGFR mRNA overexpressing cancers." (PMID 32626515, 2020). "By immunofluorescence, we found that PARP1 partially colocalized with FGFR1 in the cell nucleus in the FGFR1-expressing, PARP1-expressing PANC-1 cancer cell line." (PMID 32276472, 2020). "FGFR1 overexpression has been reported to promote endocrine therapy resistance and to decrease DMFS (Distant Metastasis Free Survival) in ER positive cancers." (PMID 32987805, 2020). "All six selected survival-related genes (EMP1, TPM1, NRP2, FGFR1, CAVIN1, and LATS2) were reported to play a positive role in disseminating cancer cells or invasion in many kinds of cancers." (PMID 32695477, 2020). "Fibroblast growth factor receptor-1 (FGFR1), known as one member of receptor tyrosine kinases (RTKs), is considered as an attractive target for cancer treatment increasingly." (PMID 33041789, 2020). "Some of these alterations are located in receptor tyrosine kinases (RTK) genes (FGFR1, FGFR2, FGFR3, and FGFR4), which have important implications for the selection of anti-cancer therapies." (PMID 32245111, 2020). "Considering age, several genes responsible for inflammatory protein secretion/activation (KLK3, EDN3), cell-adhesion (PI4KA, AHSAI1) and cancer-related proteins (KLK3, FGFR1/2, PRKACA, and RAC2) were also modulated in AYA-RMS." (PMID 31533233, 2019). "3D185 inhibited FGFR1-, FGFR2-, FGFR3-, and CSF-1R-mediated cancer cell proliferation, with IC50 values ranging from 0.9 to 36.8 nM." (PMID 31438996, 2019). "In KRAS mutant cancers, targeting of MEK with trametinib led to compensatory signaling through fibroblast growth factor receptor 1 (FGFR1)." (PMID 31681559, 2019). "In cancer cells LDHA is tyrosine phosphorylated and was found to be phosphorylated at all four tyrosine sites by fibroblast growth factor receptor 1 (FGFR1)." (PMID 31146503, 2019). "Collectively, ROR1 and FGFR1 together lead to the activation of AKT pathway and cancer cell invasion." (PMID 31137681, 2019). "Cytoscape analysis of gene network revealed important cancer pathways including hub genes at NFGR, MAPK3, and SMAD7 for OS, and hub genes at FOXP1, MAP2K5, FGFR1, and NOTCH2 for DFS." (PMID 31608231, 2019). "FGF2 is a molecule significantly more stable than FGF1, and binds to FGFR1, FGFR3 and, to a lesser extent, to FGFR2, allowing it to be a targeting molecule for a large group of FGFR-overexpressing cancers." (PMID 30029518, 2018). "The inhibition of miR-216b leads to activation of the FGFR1/ERK signaling pathway and to subsequent cancer progression of this cancer." (PMID 29755696, 2018). "Here, we found fusion genes involving BRAF, NTRK3, ALK, FGFR1, and ROS1, which result in activation of the MEK/ERK pathway in other cancers." (PMID 29654269, 2018). "FGFR1 is the main member of the FGFR family and known to be a common target of deregulation by gene amplification in several human cancers, including cancer of the breast, bladder and lung." (PMID 29734851, 2018).
cancer (continued). "Peaks involving important cancer genes such as CCND1, EGFR, ERBB2, FGFR1, AKT1, MYC, KRAS and CDKN2A/2B, which were confirmed in our data." (PMID 30131072, 2018). "In our research, we found that MAPK1, FGFR1, and PIK3R5 participate in more than 4 important cancer-related signaling pathways." (PMID 30560088, 2018). "Fibroblast growth factor receptor 1 (FGFR1), an oncogenic receptor tyrosine kinase (RTK), plays fundamental roles in physiological processes and cancer progression." (PMID 28558758, 2017). "AZD4547 is currently under a Phase II clinical trial to assess its activity in patients with FGFR1 or FGFR2 amplified breast, squamous lung, and stomach cancer whose cancers have progressed following previous chemotherapy (NCT01795768)." (PMID 28030802, 2017). "The FGFR family, and FGFR1 in particular, is highly expressed in MPM cell lines, and represents an emerging therapeutic target for cancer treatment." (PMID 28545562, 2017). "AZD4547 is a potent and selective small-molecule inhibitor of FGFR1 with an IC50 value of 0.2 nM and currently in phase II and III clinical trials for the treatment of cancer (ClinicalTrials.gov Identifier: NCT02154490)." (PMID 28806774, 2017). "When compared with normal tissues, the expression of FGFR1, FGFR2, and FGFR4 were higher and the expression of FGFR3 was lower in cancer tissues." (PMID 27154171, 2016). "FGFR1 and FGFR2 are the members of the fibroblast growth factor receptor (FGFR) family of genes with a variety of roles in cancer." (PMID 28330331, 2016). "Among them, several genes were related in cancer pathway such as EGFR, RARA, FGF2, FGFR1, FGFR2, FGFR3, KIT, and CCND1." (PMID 27016420, 2016). "The expression rate of FGFR1 was 10.4% in Lum A, 23.5% in Lum B, 4.5% in HER2-OE, and 17.9% in TNBC (11.8% in BLBC and 6.1% in unclassified) cancers." (PMID 26673008, 2016). "Characterization of the mechanism of action of IMB-R1 demonstrated that it selectively affects cancer cell survival by preventing the formation of FGF/FGFR1 complexes, thereby inhibiting the FGF/FGFR1 signaling axis." (PMID 26201468, 2015). "Particularly, many cancer-related genes including CDH5, BVES, CX3CL1, FGFR1, IGF1 and CD40 were identified in SIN_D." (PMID 25774687, 2015). "Regions of high level gain or amplification encompassed key cancer genes such as MYCN (2p), the EVI1/MDS1 cluster (3q), FGFR1 (8p), OCT4 and MYC (8q) and KRAS (12p) of which a number are potential therapeutic targets." (PMID 26334103, 2015). "Second, our pipeline was able to recapitulate most known translocation events in cancer (ALK, BRAF, EGFR, FGFR1, 2 and 3, NTRK1, 2 and 3, PDGFRA, PRKCA, RAF1, RET, ROS1)." (PMID 25204415, 2014). "Next we interrogated these physiomimetic cultures for localisation of FGFR1 and FGF2 in specific cellular compartments (within both cancer and stromal cells), upon PD173074 treatment." (PMID 24503018, 2014). "SAIC also identified many other cancer driver genes within individual chromosomes (ST 3), such as SKIL, CDK4, PIK3CA, PTEN, FGD4, FGFR1." (PMID 22839576, 2012). "In a comparison of normal and cancer tissues harvested from the mouse models mRNA expression of MLH1 and of FGFR1 showed a significant, inverse relationship miR-155 and miR-10 respectively." (PMID 21738581, 2011). "FGFR1 and INSR are both known to be involved in carcinogenesis and thus become novel, attractive targets for cancer therapeutic strategies." (PMID 21211025, 2011). "The expression levels of FGFR1 and FGFR2 are known to be upregulated in cancer cells and ECs in HNSCC." (PMID 21063405, 2010). "It has been reported that angiogenesis is enhanced and the expression levels of FGFR1 and FGFR2 are upregulated in cancer cells and ECs in HNSCC." (PMID 21063405, 2010).
cancer (continued). "In contrast to FGFR1–4, the role of FGFRL1 in cancer research remains underexplored." (PMID 41514604, 2025). "Clinically, the off-target inhibition of FGFR1 by pralsetinib may contribute to both therapeutic outcomes and adverse effects in RET-altered cancers." (PMID 41226200, 2025). "The OD-BRE-0438 model with the most resistant phenotype, as evidenced by the shortest median PFS, showed statistically significant upregulated gene expression of FGF1, FGF7, and FGF8 ligands in cancer cells, while FGFR1, FGFR2, or FGFR3 were not upregulated." (PMID 40227585, 2025). "Another MRTKi, infigratinib (a potent inhibitor of FGFR1-3) has also shown promising results in pre-clinical testing in vitro and in vivo, particularly against FP-RMS, but clinical testing has so far been restricted to adult cancer types." (PMID 40469193, 2025). "Importantly, representative compounds, including 13f, 19e, and 22f, exhibited strong inhibition across FGFR1–4 and robust antiproliferative efficacy in both FGFR-driven and wild-type cancer models." (PMID 41304987, 2025). "FGFR1 gains and amplifications are the most common FGFR alterations in cancer." (PMID 40016412, 2025). "In addition to the receptors FGFR1, FGFR4 and ERBB4, the main effector AKT1 and its downstream effectors, MTOR, GSK3B, p21, WEE1, BAD and CREB5, which mediate cancer cell growth and progression, also exhibited marked changes in HPV-ind CCs." (PMID 38253702, 2024). "In this study, we compared the impact of FGF2 on cell growth and cancer stemness states in two groups of cancer cells, with and without FGFR1 amplification." (PMID 38553760, 2024). "Next, we wanted to test whether inhibition of FGFR1 activity by honokiol and FGF ligand trap in cancer cells with low levels of FGF receptors could reverse the acquisition of long-term multidrug resistance." (PMID 39329123, 2024). "Our results shed light on how blocking the FGF1/FGFR1 axis by honokiol and FGF ligand trap could help develop more effective cancer therapies, potentially preventing the emergence of drug-resistant relapses." (PMID 39329123, 2024). "Exon skipping in genes such as TUBB6, FGFR1, cAMP-dependent protein kinase inhibitor gamma (PKIG), and METTL5 was observed, which could lead to the development of cancer or affect a normal function of nervous system." (PMID 40395612, 2024). "In addition, we observed via immunocytochemistry that FGFR1 and VEGFR2 were expressed in cancer cells engaged in VM, and intriguingly, they were also present in vesicles inside MMECs." (PMID 37762073, 2023). "First, we were able to show that FGFR1 was expressed not only in the TNBC cells engaged in VM but also in the ECs and MMECs neighboring the branches of the cancer networks, strongly suggesting the involvement of this receptor in intercellular communication during VM." (PMID 37762073, 2023). "The increased expression of FGFR1 and VEGFR2 in cancer VM-forming cells, along with their specific localization pattern within the MMECs of the CCs, suggest an important role for these receptors in intercellular communication, possibly contributing to the formation of VM structures." (PMID 37762073, 2023). "Furthermore, multiple previous studies have indicated the presence of shared signaling pathways, such as the PI3K pathway, FGFR1 pathway between LUSC and CRC, implying potential common genetic origins and developmental processes between these two cancer types." (PMID 37840123, 2023). "In addition, gene network analysis regarding to mass-type ER-positive cancers showed that ESR1, BIRC5, CAV1, FGFR1, IL6, MIR27, and PTTG1 were upregulated." (PMID 37391754, 2023). "To examine whether FGFR inhibitors inhibit the efflux of chemotherapeutic agents from Tx-R cancer cells, we performed FACs analysis of cancer cells treated with PTX or Dox alone and in presence of BGJ 398 (the potent and selective inhibitor of FGFR1-4)." (PMID 35327403, 2022).